SHMT2 (serine hydroxymethyltransferase 2)
Diseases named in the same sentence as SHMT2 in open-access papers (continued):
Sharing a sentence is not in itself a finding about the gene and the disease.
pancreatic ductal adenocarcinoma (1 paper, 2025). An infiltrating adenocarcinoma that arises from the epithelial cells of the pancreas. "SHMT2 is significantly upregulated in pancreatic ductal adenocarcinoma tissues and is localized in the cytoplasm of tumor cells." (PMID 40738465, 2025). "Immunohistochemical analyses of 103 pancreatic ductal adenocarcinoma samples revealed that high SHMT2 expression was significantly associated with poor OS but not with DFS." (PMID 40738465, 2025).
papillary thyroid cancer (1 paper, 2024). "Here, we reveal that serine hydroxymethyltransferase-2 (SHMT2) generates S-adenosylmethionine (SAM) to epigenetically repress phosphatase and tensin homolog (PTEN), leading to papillary thyroid cancer (PTC) metastasis depending on activation of AKT signaling." (PMID 38272883, 2024).
Sepsis (1 paper, 2022). Sepsis is defined as life-threatening organ dysfunction caused by a dysregulated host response to infection. "Given that sepsis dysregulates glycine metabolism in mice, we examined whether DCA might blunt glycine deficiency during sepsis by assessing GNMT, SARDH, SHMT1, and SHMT2, the key enzymes involved in glycine metabolism." (PMID 35730570, 2022).
steatosis (1 paper, 2024). Increased lipid within the cytoplasm of cells. "It is possible that additional SHMT2 activity is required to activate the liver’s immune and fibrogenic response to steatosis and injury." (PMID 38347107, 2024).
undifferentiated thyroid carcinoma (1 paper, 2024). "Collectively, we found that SHMT2 and MTHFD2 were significantly associated with low TDS and aggressive clinico-pathological features, supporting the importance of the mitochondrial one-carbon pathway in undifferentiated thyroid carcinoma." (PMID 38331894, 2024).
viral infection (1 paper, 2025). "Seven of these acetylated proteins, including DDX3X, PTBD, TRIM56, IPO7, PPID, SHMT2, and ZC3HAV1, have been implicated in innate immunity and viral infection, based on functional annotation using databases such as GO Biological Process, KEGG and reactome." (PMID 39747662, 2025).
cancer (165 papers, 2013 to 2025). A tumor composed of atypical neoplastic, often pleomorphic cells that invade other tissues. "According to the analysis from multiple databases such as TCGA, SHMT2 is highly expressed in various cancers and is significantly associated with poor prognosis in BLCA." (PMID 41347062, 2025). "Riboregulation is not limited to SHMT2 but can potentially be applied to control the activity of other RNA-binding metabolic enzymes implicated in cancer and other diseases." (PMID 40770176, 2025). "The upregulation of SHMT2 in cancer cells was mainly caused by enhanced protein stability, and phosphorylation played a key role in this process." (PMID 38460155, 2024). "Accumulating evidence suggests that SHMT2, a key enzyme in one-carbon unit metabolism, is remarkably associated with malignant progression of several human cancers." (PMID 37932821, 2023). "A large-scale comparative oncogenomics study of 392 primary human cancers showed that overexpression of SHMT2 was necessary for tumor cell survival and associated with poor prognosis in human cancer." (PMID 36806313, 2023). "Serine hydroxymethyltransferase 2 (SHMT2) has been reported to be upregulated in several cancers and associated with poor prognosis." (PMID 37932821, 2023). "It reported that SHMT2 is upregulated and associated with tumor progression in a variety of cancers." (PMID 37932821, 2023). "Upregulation of SHMT2 is found in several cancers and is associated with increased tumor aggressiveness." (PMID 35018218, 2022). "Serine hydroxymethyltransferase 2 (SHMT2) regulates serine metabolism in a myc-dependent manner; it is upregulated in several cancers and is associated with tumor aggressiveness." (PMID 35018218, 2022). "Altered serine metabolism has been linked to several cancer types and has been shown to be affected in a myc-dependent manner by mitochondrial serine hydroxymethyltransferase 2 (SHMT2)." (PMID 35018218, 2022). "Extensive literature has demonstrated the important catalytic function of SHMT2 in various human cancers and its association with tumor growth." (PMID 35333683, 2022). "High levels of SHMT2 are associated with poor patient prognosis in several cancers and inhibitors that target both SHMT2 and SHMT1 (which catalyzes the same reaction in the cytoplasm) have shown promising results in initial cellular and mouse studies." (PMID 34368168, 2021). "The mitochondrial isoform of SHMT2 is found to be upregulated in many cancers including CRC, associated with tumor invasiveness and poor prognosis." (PMID 34200820, 2021). "Among these genes, SHMT2, which encodes one of the most prominent enzymes in cancer metabolism, has been little studied in CRC, which inspired us to investigate further." (PMID 33990700, 2021). "On the one hand, an increased expression of the active metabolic enzyme SHMT2 is associated with various types of cancer." (PMID 34440217, 2021). "We therefore envisioned that the anti-proliferative effects of metformin would be affected by the loss of its putative SHMT2 target in cancer cells." (PMID 34439169, 2021). "Overexpression of SHMT2 has been found in cancers and associated with poor prognosis in cancer patients." (PMID 32111066, 2020). "SHMT2 is linked to several aspects of metabolism important to cancer cell survival and proliferation." (PMID 32903271, 2020). "Gene set enrichment analysis found that SHMT2 was significantly associated with cancer invasion and poor survival among breast cancer patients." (PMID 30228815, 2018). "It has been found that inhibition of serine metabolism, by serine starvation or RNAi knockdown of SHMT2, caused accumulation of precursors and inhibition of cancer cell proliferation, by depleting 1C carbon units for purine biosynthesis." (PMID 29342092, 2018).
cancer (continued). "The meta-analysis of gene expression in different cancers has also shown that high level of SHMT2 expression associates with decreased patient's outcome, which suggests that up-regulation of SHMT2 is a common event common between different malignancies." (PMID 28177894, 2017). "Several recent papers describe SHMT2 upregulation in several cancer cell types, including colon and breast, underlying the relevance of this isoform in the metabolism of specific cancer cells, where it is upregulated possibly to counteract redox stress." (PMID 26717037, 2016). "We have further identified that loss of AGL promotes rapid cancer cell proliferation dependent on extracellular glucose, Serine Hydroxymethyltransferase 2 (SHMT2) driven glycine synthesis and Hyaluronic Acid (HA) Synthase 2 (HAS2) mediated HA synthesis." (PMID 27595989, 2016). "Through isotopomer tracing of [2–13C] glycine metabolism, we demonstrated that SHMT2 activity is associated with cancer phenotype." (PMID 27391339, 2016). "In summary, the DEG results suggest that SHMT2 could affect expression of a small set of genes that were associated with cancer development, indicating a potential novel regulatory mechanism for SHMT2 in HT-1376 cells." (PMID 41347062, 2025). "Furthermore, SHMT2 has been implicated in conferring resistance to apoptosis by modulating the cellular redox state, thereby enabling cancer cells to evade programmed cell death mechanisms." (PMID 40432803, 2025). "Increased SHMT2 is also associated with cancer drug resistance in a few drugs." (PMID 39189649, 2024). "SHMT2 expression is high in several forms of cancer and is associated with a poor prognosis." (PMID 36358687, 2022). "Importantly, high expression of both ILF2 and SHMT2 was discovered to be closely associated with cancer metastasis." (PMID 35333683, 2022). "In addition, given SHMT2 is upregulated in several cancers, elucidating the mechanism underlying SHMT2 in NB will aid the development of potential therapies with broad applications." (PMID 35018218, 2022). "SHMT2 overexpression has been linked to poor outcome in cancer patients." (PMID 34944586, 2021). "Notably, serine catabolism is elevated in cancer, and the genes encoding MTHFD2 and SHMT2 are among the top five differentially expressed genes in tumors and normal tissues for a wide range of cancers, including EOC." (PMID 35008360, 2021). "Therefore, SHMT2 was associated with tumor invasiveness in multiple cancer types and could predict the prognosis of patients with lung metastases from breast cancer." (PMID 36998464, 2023). "SHMT2 catalyses the rate‐limiting step of serine metabolism and is known to play an important role in the proliferation of cancer cells as it promotes metabolic reprogramming." (PMID 40172090, 2025). "Serine hydroxymethyltransferases (SHMTs) are key proteins that regulate carbon (methyl) metabolism, including the cytoplasmic isoenzyme (SHMT1) and the mitochondrial isoenzyme (SHMT2), and play a role in metabolic reprogramming in cancers." (PMID 40442541, 2025). "This modified RNA, referred to as mUTR2, selectively inhibits SHMT2 activity in mitochondria, resulting in reduced cancer cell viability." (PMID 40770176, 2025). "Then we checked the expression level of SHMT2 in different cancer stages of BLCA patients, and found that SHMT2 showed significant increase in all stages." (PMID 41347062, 2025). "Specifically, SHMT2 lactylation enhances one-carbon metabolism and supports nucleotide synthesis, thereby sustaining the proliferative capacity of cancer stem-like cells." (PMID 41458606, 2025). "And some evidences showed that SHMT2 overexpression supports cancer cell survival in melanoma cells." (PMID 40432803, 2025). "Lactylation modifies SHMT2, promoting glycolysis and tumor proliferation, while H4K12la plays a crucial role in cancer stem cell characteristics." (PMID 41458606, 2025).
cancer (continued). "SHMT2, often overexpressed in various cancers, is pivotal in one-carbon metabolism, a pathway vital for cell proliferation." (PMID 40770176, 2025). "In the present work we explored the therapeutic potential of this natural regulatory mechanism to target SHMT2 in cancer cells." (PMID 40770176, 2025). "Given their distinct metabolic functions, targeting SHMT1 and SHMT2 is a promising therapeutic strategy for cancer and metabolic diseases." (PMID 40738465, 2025). "For instance, research has shown that overexpression of SHMT2 is correlated with enhanced proliferation and invasion capabilities in different cancers, including LUAD." (PMID 40432803, 2025). "Given that the serine cleavage reaction, which is the most relevant to cancer metabolism, is mainly carried out in the cells by SHMT2 within the mitochondrial compartment, our next goal was to address the inhibitory RNA to this compartment." (PMID 40770176, 2025). "This process is vital for DNA replication and repair, making SHMT2 indispensable for rapidly proliferating cells, such as cancer cells." (PMID 40432803, 2025). "SHMT2, a mitochondrial enzyme central to one-carbon metabolism, is often overexpressed in cancer cells, where it meets specific metabolic demands and drives tumor progression." (PMID 40770176, 2025). "Meanwhile, the enriched KEGG pathway endocytosis is an emerging feature of cancer and a pivotal pathway for regulating metastasis, indicating that the AS regulation is a promising regulatory manner of SHMT2 in BLCA progression." (PMID 41347062, 2025). "Large-scale genomic study of human tumors reveals that SHMT2 is essential for cancer cell survival and its knockdown severely impairs cancer cell proliferation." (PMID 38218942, 2024). "One beneficial function of SHMT2 in cancer cells is that it can help the cancer cells in hypoxic environments." (PMID 39189649, 2024). "The high expression percentages of SHMT2 in cancer and normal tissues were 56.4% and 38.75%, respectively (P = 0.018)." (PMID 38188143, 2024). "SHMT1 and SHMT2 are the key enzymes in 1C metabolism and have been studied as cancer therapeutic targets." (PMID 38279895, 2024). "Enzymes of the SSP, SHMT1 and SHMT2 (cytoplasmic and mitochondrial isoform, respectively), as well as downstream one-carbon metabolism enzymes are overexpressed in numerous cancers compared to the normal tissues." (PMID 38515202, 2024). "The transcriptome and proteome of SHMT2 pan-cancer were further validated, and SHMT2 was found to be generally highly expressed in tumors." (PMID 38625586, 2024). "The results of IHC staining revealed that the high expression rates of SHMT2 in precancerous tissues and cancer tissues were 38.75% and 56.44%, respectively." (PMID 38188143, 2024). "The results showed that SHMT2 expression was much higher in cancer tissues than in adjacent normal tissues." (PMID 38460155, 2024). "In fact, posttranslational modifications are important for the expression and activity of SHMT2 in some types of cancer." (PMID 38460155, 2024). "Serine hydroxymethyltransferase 2 (SHMT2) plays a key role in one-carbon metabolism and influences the proliferation and growth of cancer cells." (PMID 39309860, 2024). "Recent studies have shown that overexpression of SHMT2 is observed in a variety of cancers, including breast, melanoma, lung, ovarian, and prostate cancers, and that it is associated with tumorigenesis and progression." (PMID 38625586, 2024). "Serine hydroxymethyltransferase 2 (SHMT2) constitutes one of the most prominently expressed metabolic enzymes in human carcinomas and is markedly elevated in EC tissues and cells." (PMID 39867891, 2024). "PKM2 activity was upregulated in cancer cells with experimentally suppressed SHMT2 expression, suggesting that lower levels of SHMT2 promote PKM2-mediated production of pyruvate and ATP, which ultimately supports cell proliferation." (PMID 36959541, 2023).
cancer (continued). "Serine hydroxymethyltransferase 2 (SHMT2) plays an important role in converting serine to glycine and supplying carbon to one-carbon metabolism to sustain cancer cell proliferation." (PMID 36806313, 2023). "The directionality of serine/glycine conversion is a significant factor for cancer cell metabolism and evidence indicates that mitochondrial SHMT2 is the main serine-glycine converting enzyme." (PMID 36793607, 2023). "Among them, SHMT2 is considered to be an important factor in the metabolism of serine and glycine of several cancer cell types (including BC), which is crucial in the development of cancer cells, and high SHMT2 expression is linked to poor prognosis in BC." (PMID 38239641, 2023). "Serine is the major source of one-carbon units in cancer cells and serine catabolism by SHMT2 is essential for maintaining mitochondrial respiration, redox control and proper mitochondrial translation initiation." (PMID 37749499, 2023). "Folate metabolism can produce mitochondrial NADPH through ALDH1L2 and potential MTHFD2, and the knockdown of SHMT2 in some cancer cell lines increases their vulnerability to oxidative stressors." (PMID 37147729, 2023). "In poorly vascularized tumor regions, cancer cells depend on serine and glycine metabolism for survival, highlighted by high levels of mitochondrial serine hydroxymethyltransferase (SHMT2) and glycine decarboxylase (GLDC)." (PMID 37298093, 2023). "Curcumin binds to SHMT2, and there is a high probability that the binding impacts both the structure and the catalytic activity of the active form of SHMT2, which was recently shown to drive resistance to 5-FU in a colorectal model of cancer." (PMID 37376060, 2023). "SHMT2, an essential enzymefor cancer metabolic reprogramming, catalyzes the reversible reaction of serine to glycine by transferring the β-carbon from serine toTHF." (PMID 37108312, 2023). "Mitochondrial serine hydroxymethyltransferase (SHMT2) is required for cancer cells to adapt to the tumor environment." (PMID 36703877, 2023). "Compared with SHMT1, SHMT2 also exists in various cancers via the conversion of serine and glycine in mitochondria to support cancer cell proliferation." (PMID 37009511, 2023). "Human SHMT2 (hSHMT2) has been found to be highly overexpressed in many types of cancers as a result of metabolic reprogramming of the one-carbon metabolism." (PMID 37532884, 2023). "Knockdown of SHMT2 in colorectal cancer xenografts completely blocked cancer development only when SHMT1 was also downregulated." (PMID 37664062, 2023). "SHMT2 is the mitochondrial isoform that catalyzes the conversion of serine to glycine and is essential for providing glycine in proliferating cancer cells." (PMID 36175487, 2022). "SHMT2, a key regulator in the serine/glycine metabolism pathway, is involved in cancer proliferation." (PMID 35114976, 2022). "In the current study, we showed that SHMT2 is closely related to cancer cell stemness by performing Gene Ontology (GO) and Kyoto Encyclopedia of Genes and Genomes (KEGG) pathway enrichment analyses in The Cancer Genome Atlas (TCGA) dataset for HNC." (PMID 36077112, 2022). "It has been reported that SHMT2, a key metabolic enzyme, can regulate cancer cell regulation and metabolism." (PMID 35333683, 2022). "Serine hydroxymethyltransferase 2 (SHMT2) has a critical role in serine-glycine metabolism to drive cancer cell proliferation." (PMID 35211429, 2022). "Two such mitochondrial proteins, MTHFD2 and SHMT2, are among the most differentially expressed metabolic enzymes in cancer cells compared to normal cells." (PMID 34341479, 2022). "Similar studies on the mitochondrial folate metabolism enzymes revealed a link between cancer and aberrant SHMT2 and MTHFD2 expression." (PMID 36551330, 2022). "The association between SHMT2 and PI3K/Akt in hepatocyte regeneration has been well established but its mechanistic interaction in cancer has yet to be clearly elucidated." (PMID 35018218, 2022).